VGLL1 (vestigial like family member 1)
Description:
May act as a specific coactivator for the mammalian TEFs.
Synonyms: TDU; TONDU; VGL1
Tractability: PROTAC: ubiquitination databases record sites on it.
Gene: Protein-coding gene on chromosome X (136,532,154 to 136,556,807, forward strand). Ensembl gene ENSG00000102243.
Subcellular location: Nucleus
Subcellular location (Human Protein Atlas): Nucleoplasm
Gene Ontology:
Molecular function: protein binding; transcription coactivator activity
Biological process: regulation of DNA-templated transcription; regulation of transcription by RNA polymerase II; positive regulation of DNA-templated transcription
Cellular component: nucleoplasm; nucleus
Homologues: Orthologues: chimpanzee VGLL1 (98% identical), macaque VGLL1 (97% identical), dog VGLL1 (52% identical), mouse Vgll1 (47% identical), tropical clawed frog vgll1 (27% identical), Drosophila melanogaster vg (14% identical). Paralogues in human: VGLL3 (27% identical), VGLL2 (25% identical).
Diseases named in the same sentence as VGLL1 in open-access papers:
VGLL1 is named in the same sentence as 29 diseases in open-access papers, as found by Europe PMC text mining. Sharing a sentence is not in itself a finding about the gene and the disease. The quoted sentences say what the papers report.
breast carcinoma (8 papers, 2015 to 2024). "Echoing its role in the placenta, VGLL1 expression has previously been linked to increased cell proliferation in basal-like breast cancer, estrogen receptor-positive breast cancer, gastric cancer, pancreatic cancer, prostate cancer and HPV-related cervical cancer." (PMID 38912065, 2024). "Expression of VGLL1 and its intronic miRNA miR-934 are associated with sporadic and BRCA1-associated triple negative basal-like breast carcinomas." (PMID 39484215, 2024). "The aim of this study was to evaluate the cellular function and downstream genomic targets of VGLL1 in placental, pancreatic, and breast cancer cells." (PMID 38912065, 2024). "Clinical studies have shown that higher tumor VGLL1 expression correlates with lower overall survival in pancreatic cancer, gastric cancer, basal-like breast cancer, and breast cancers that become resistant to SERD therapy." (PMID 38912065, 2024). "Its expression is upregulated in a variety of aggressive cancer types, including pancreatic and basal-like breast cancer, and increased transcription of VGLL1 is strongly correlated with poor prognosis and decreased overall patient survival." (PMID 38912065, 2024). "TCGA RNAseq data analysis indicated that VGLL1 is expressed by several additional cancer types (16 of 34 total), most notably in 75–80% of patients with bladder, ovarian, and basal-type breast cancers, and 15–20% of patients with lung and gastric cancers." (PMID 33087697, 2020). "Within breast cancer samples, VGLL1-4 expression patterns varied considerably across different histologic subtypes (data not shown)." (PMID 28733631, 2017). "Interestingly, VGLL1 appears to be preferentially expressed in basal-like breast cancers while demonstrating a relatively low prevalence in other breast cancer subtypes." (PMID 33087697, 2020). "To overcome this limitation, we examined VGLL1-4 expression levels in a panel of 30 breast cancer cell lines that mirror most of the important genomic and resulting transcriptional abnormalities found in primary breast tumors and have been extensively used in mechanistic studies." (PMID 28733631, 2017). "Based on the elevated VGLL1 transcript expression reported in particular tumor types, we screened pancreatic cancer (PDAC), basal-like breast cancer (BLBC), and choriocarcinoma (a placenta-derived tumor) cells for VGLL1 protein expression." (PMID 38912065, 2024). "When we applied heteroDE to breast cancer samples, we identified 7 cfRNA biomarkers (SCGB2A2, CASP14, FABP7, CRABP2, VGLL1, SERPINB5, TFF1), 3 of which (FABP7, SCGB2A2, CASP14) overlap with previously identified DCB genes." (PMID 33883548, 2021). "Immediate clinical applications of these findings include a planned clinical trial to treat HLA-A*0101+/VGLL1+ PDAC patients with VGLL1-specific ETC therapy, with future cohorts to potentially include bladder, ovarian, and/or breast cancer patients." (PMID 33087697, 2020). "Three transcription factors, GRHL1, VGLL1, and ELF5 are strong candidates for the cell autonomous regulation of ST14/Prss14 in basal type ER− breast cancer patients and ER+ luminal A type breast cancer cell lines." (PMID 27167193, 2016). "Here, we report that diminished VGLL4 expression, but not VGLL1-3, correlated with both shorter relapse-free survival and shorter disease-specific survival of cancer patients with different molecular subtypes of breast cancer." (PMID 28733631, 2017). "Furthermore, we found that VGLL1-4 expression did not correlate with tumor grade and showed no capacity to stratify breast cancer patients into good versus poor outcome groups." (PMID 28733631, 2017). "Furthermore, dysregulation of VGLL4 expression, but not VGLL1-3, is commonly observed in patients with different molecular subtypes of breast cancer and correlated with a poor patient prognosis." (PMID 28733631, 2017).
breast carcinoma (continued). "Here we show that VGLL1-specific CTLs expanded from the blood of a PDAC patient could recognize and kill in an antigen-specific manner a majority of HLA-A*0101 allogeneic tumor cell lines derived not only from PDAC, but also bladder, ovarian, gastric, lung, and basal-like breast cancers." (PMID 33087697, 2020).
gastric cancer (5 papers, 2019 to 2024). A primary or metastatic malignant neoplasm involving the stomach. "In gastric cancer, we confirmed that VGLL1, which has a similar structure to TAZ, binds with TEAD4 to the integrin αV promoter in the presence of TNF-α." (PMID 36613819, 2022). "In this study, we discovered VGLL1 as a novel prognostic biomarker correlated with PIK3CA or PIK3CB in gastric cancer." (PMID 31816819, 2019). "LY294002, a class I PI3K inhibitor, downregulated VGLL1 mRNA and protein levels in a dose-dependent manner in gastric cancer cell lines." (PMID 31816819, 2019). "We explored 172 genes in the subgroup with high VGLL1 expression to gain insights into the role of VGLL1 in gastric cancer." (PMID 31816819, 2019). "We observed that VGLL1 promoted the proliferation and tumorigenesis of gastric cancer cells in in vitro cell culture and in vivo xenograft mouse models." (PMID 31816819, 2019). "VGLL1 expression was positively correlated with PIK3CA and PIK3CB, which are associated with poor OS in gastric cancer patients." (PMID 31816819, 2019). "Next, we performed microarray analyses of specimens from 556 gastric cancer patients to understand the clinical relevance of VGLL1." (PMID 31816819, 2019). "We assessed the clinical relevance of VGLL1 in gastric cancer by immunohistochemistry (IHC) of gastric cancer specimens." (PMID 31816819, 2019). "PI3K/AKT/β-catenin transcriptionally activates VGLL1, thus calibrating MMP9 expression linked to gastric cancer malignancy." (PMID 31816819, 2019). "Taken together, we clearly elucidated the molecular mechanism that involves VGLL1 that promotes malignancy in gastric cancer, thus suggesting VGLL1 as a therapeutic target in treatment of gastric cancer." (PMID 31816819, 2019). "Here, we present the regulation mechanism of VGLL1 to induce MMP9 expression that promotes gastric cancer malignancy." (PMID 31816819, 2019). "Here, we investigated the clinical relevance and molecular function of VGLL1 in gastric cancer through in vitro experiments and in vivo mouse models." (PMID 31816819, 2019). "Taken together, PI3K/AKT/β-catenin signaling regulates the transcription of VGLL1, which promotes the proliferation and metastasis in gastric cancer." (PMID 31816819, 2019). "Microarray analysis of 556 gastric cancer tissues revealed that VGLL1 was a prognostic biomarker that correlated with PI3KCA and PI3KCB." (PMID 31816819, 2019). "Here, we investigate molecular function and regulatory mechanisms of Vestigial-like 1 (VGLL1) in gastric cancer." (PMID 31816819, 2019). "VGLL1 regulates the proliferation of gastric cancer cells, as shown in live cell imaging, sphere formation, and in vivo xenograft model." (PMID 31816819, 2019). "Finally, we observed that the VGLL1 S84 peptide inhibited the invasion of gastric cancer cells increased by coculture with RAW264.7 cells." (PMID 36613819, 2022). "Furthermore, it was confirmed that the correlation between VGLL1 and integrin αV expression in gastric cancer patients was significant." (PMID 36613819, 2022). "Importantly, transient expression of constitutively active AKT containing S473D/T308D double mutation rescued VGLL1 expression in the presence of LY294002, which suggested that PI3K/AKT signaling regulates VGLL1 transcription in gastric cancer cells." (PMID 31816819, 2019). "In addition, VGLL1 overexpression has been shown to increase cell invasion in gastric cancer cells." (PMID 38912065, 2024). "In comparison to most normal tissues VGLL1 is overexpressed in several different cancers, including PDAC, bladder, ovarian, breast, lung, and stomach cancer." (PMID 33087697, 2020). "We selected MMP9 as a potential VGLL1-targeted gene, because high MMP expression is correlated with metastasis and poor prognosis in gastric cancer." (PMID 31816819, 2019). "VGLL1 is a prognostic biomarker that correlates with PIK3CA and PIK3CB in gastric cancer." (PMID 31816819, 2019).
gastric cancer (continued). "Although HEK293T are not gastric cancer cells, these results are suggestive, but they do not prove that VGLL1 is important for the increased proliferation of xenografts." (PMID 31816819, 2019).
pancreatic cancer (3 papers, 2020 to 2024). "VGLL1 is also overexpressed in multiple cancer types, demonstrating predominant expression in basal-like breast and pancreatic cancers with transcription increased by 8- to 60-fold compared to normal breast and pancreatic tissue." (PMID 38912065, 2024). "A novel 14-gene signature comprising CCDC148, SH3RF2, CACNA1D, POLD3, PARP1, AP1M2, C4orf19, ANO1, VGLL1, SCEL, INPP4B, NET1, INSIG2 and BVES and a corresponding risk score formula were established for pancreatic cancer risk stratification and prognosis prediction." (PMID 33731794, 2021).
bladder cancer (2 papers, 2020 to 2025). "Interestingly, low or absent VGLL1 expression was associated with shorter survival time in bladder cancer (p = 0.036)." (PMID 33087697, 2020).
breast tumor (2 papers, 2017 to 2020). "The analysis of VGLL1 expression in human breast tumor revealed that increased expression of VGLL1 is often detected in malignant types of breast tumor (triple negative and basal-like) and that VGLL1 expression is associated with reduced overall survival." (PMID 32793503, 2020).
gastric tumor (2 papers, 2020). "Increased expression of VGLL1 has also been reported in gastric tumor, and its correlation with phosphatidylinositol-3-phosphate kinases (PI3K)/AKT/β-catenin signaling has also been demonstrated." (PMID 32793503, 2020). "VGLL1 is required for gastric tumor cell growth and metastasis, and matrix metalloprotease 9 (MMP9) has been suggested to be a target of VGLL1-TEAD4 complex." (PMID 32793503, 2020).
ovarian carcinoma (2 papers, 2020 to 2024). A malignant neoplasm originating from the surface ovarian epithelium. "Pancreatic, triple negative breast, gastric, and HPV-related cancers such as ovarian cancer show the highest levels of VGLL1 mRNA expression, and increased transcription of VGLL1 is strongly correlated with poor prognosis and lower overall patient survival." (PMID 38912065, 2024).
cervical tumor (1 paper, 2020). "Because TEAD1 activates the early promoter of human papillomavirus (HPV), a causative agent for cervical tumor, the contribution of VGLL1 to HPV early gene expression was recently investigated." (PMID 32793503, 2020).
choriocarcinoma (1 paper, 2024). An aggressive malignant tumor arising from trophoblastic cells. "Disruption of VGLL1 expression in the placenta can also lead to pathological conditions associated with preeclampsia and choriocarcinoma." (PMID 38912065, 2024). "In addition to choriocarcinoma, VGLL1 has been shown to be highly overexpressed in a variety of other cancer types." (PMID 38912065, 2024).
frontal lobe tumor (1 paper, 2026). "This frontal lobe tumor, which histologically intermingled with the neuropil andcontained a mixture of areas recognizable as schwannoma and others of primitiveappearance reminiscent of neuroblastoma, was only correctly diagnosed following thedemonstration of an EWSR1::VGLL1 fusion." (PMID 41522855, 2026).
lung carcinoma (1 paper, 2020). "Western blot analysis of a panel of ovarian, basal-type breast, bladder, gastric, and lung cancer cell lines showed high VGLL1 expression in 11 of 13 lines analyzed." (PMID 33087697, 2020).
melanoma (1 paper, 2020). A malignant, usually aggressive tumor composed of atypical, neoplastic melanocytes. "Mel888 melanoma cells (VGLL1-negative, HLA-A*0101-positive) pulsed with titrated amounts of VGLL1 peptide elicited recognition and killing at peptide concentrations as low as 10 nM, indicating relatively high affinity for cognate peptide." (PMID 33087697, 2020).
placental tumor (1 paper, 2024). "For example, GATA3 and AP2 gamma (TFAP2C), two TFs that were recently reported to cooperate with TEAD4 and VGLL1 to differentiate pluripotent stem cells into trophoblast stem cells, were also identified from our ChIP-seq analysis of breast and placental tumor cells." (PMID 38912065, 2024).
prostate tumor (1 paper, 2020). "VGLL1 was detected in human prostate tumor cell lines PC3 and LnCAP, and stable expression of VGLL1 enhanced anchorage-independent growth on soft agar." (PMID 32793503, 2020).
sarcoma (1 paper, 2020). A usually aggressive malignant neoplasm of the soft tissue or bone. "VGLL1 dysregulation was detected in various types of tumor; however, gene alterations in VGLL2 and VGLL3 were observed specifically in sarcoma." (PMID 32793503, 2020).
synovial sarcoma (1 paper, 2026). "In humans, VGLL1 is exclusively expressed in theplacenta, a tissue distribution shared with frizzled homologue 10(FZD10), an oncogene overexpressed in synovial sarcomas." (PMID 41522855, 2026).
cancer (10 papers, 2015 to 2025). A tumor composed of atypical neoplastic, often pleomorphic cells that invade other tissues. "Since the hippo pathway has been strongly implicated in the tumorigenesis of many cancer types, this study shed important light on the potential functional role of VGLL1 in cancer." (PMID 38912065, 2024). "VGLL1 has been proven to play a crucial role in various cancer types, with its high expression often associated with lower overall survival." (PMID 38918587, 2024). "Higher VGLL1 expression has been associated with shorter patient survival in multiple cancer types, including triple-negative breast and endometrial cancers." (PMID 33087697, 2020). "Since VGLL1 is a transcriptional co-activator that binds to the TEA domain (TEAD) family of transcription factors implicated in cancer development, we examined VGLL1 transcript expression in the 33 cancer types listed in TCGA." (PMID 33087697, 2020). "Thus, our analysis identified two biologically distinct cancer cell types, Ep_VGLL1 and Ep_KRT6A, that are associated with bad prognosis." (PMID 38297291, 2024). "We next assessed if tumor VGLL1 transcript expression was associated with cancer patient survival." (PMID 33087697, 2020). "This work expands our mechanistic understanding of VGLL1 function in tumor cells and provides a strong rationale for developing VGLL1-targeted therapies for treating cancer patients." (PMID 38912065, 2024). "Further studies will be required to delineate how VGLL1 cooperates with these TFs at intron regions to drive normal development in the placenta and disease progression in cancer cells." (PMID 38912065, 2024). "Comparing the eight TFs identified to interact with VGLL1 in all three tumor cell lines, we assessed the similarity in target loci found in the different cancer cells with publicly available ChIP-seq data for the same TFs." (PMID 38912065, 2024). "To evaluate the impact of VGLL1 expression on cancer cell proliferation, we monitored cell growth of these genetically altered and control cells for 7 days." (PMID 38912065, 2024). "Using a combination of cellular assays, ChIP-seq, and RNA-seq analyses, our study confirmed and extended prior findings by comprehensively assessing the downstream impact of VGLL1 expression in pancreatic, basal-like breast and placenta-derived cancer cells." (PMID 38912065, 2024). "Although little is known about the precise role VGLL1 plays in placental development, aberrantly elevated expression of this gene has also been observed in several aggressive cancer types." (PMID 38912065, 2024). "Together, these observations provide a compelling rationale for developing a VGLL1-targeted therapy for those cancer patients whose tumors demonstrate high VGLL1 expression." (PMID 38912065, 2024). "Most importantly, we discovered that Ep_VGLL1 was spatially correlated with both classical (Ep_TRIM54) and basal-like cancer (Ep_KRT6A) clusters." (PMID 38297291, 2024). "VGLL1 is thought to play a role in the Hippo signaling pathway, which controls organ size and is co-opted in multiple cancers to drive tumor progression." (PMID 33087697, 2020). "In terms of safety profile, cancer prevalence, and immunogenicity, VGLL1 compares favorably with other known TAA targets." (PMID 33087697, 2020). "MS-based identification of additional VGLL1 epitopes restricted to other HLA allotypes is also ongoing, with the promise of expanding the number of treatment-eligible cancer patients." (PMID 33087697, 2020). "Taken together, these results suggest that VGLL1 CTLs have potential therapeutic value for at least five additional cancer types besides PDAC." (PMID 33087697, 2020). "The MMP9 levels were elevated in metastasized cancer cells in the lungs and liver in a VGLL1-overexpressing NUGC3 xenograft model." (PMID 31816819, 2019). "Finally, ChIP-seq analysis was performed to identify and compare the chromosomal loci with which VGLL1 interacts in the three different cancer cell types." (PMID 38912065, 2024).